KCTD11 (potassium channel tetramerization domain containing 11)
Description:
Plays a role as a marker and a regulator of neuronal differentiation; Up-regulated by a variety of neurogenic signals, such as retinoic acid, epidermal growth factor/EGF and NGFB/nerve growth factor. Induces apoptosis, growth arrest and the expression of cyclin-dependent kinase inhibitor CDKN1B. Plays a role as a tumor repressor and inhibits cell growth and tumorigenicity of medulloblastoma (MDB). Acts as a probable substrate-specific adapter for a BCR (BTB-CUL3-RBX1) E3 ubiquitin-protein ligase complex towards HDAC1. Functions as antagonist of the Hedgehog pathway on cell proliferation and differentiation by affecting the nuclear transfer of transcription factor GLI1, thus maintaining cerebellar granule cells in undifferentiated state, this effect probably occurs via HDAC1 down-regulation, keeping GLI1 acetylated and inactive. When knock-down, Hedgehog antagonism is impaired and proliferation of granule cells is sustained. Activates the caspase cascade.
Synonyms: C17orf36; REN; KCASH1; REN/KCTD11
Tractability: No criterion of Open Targets' tractability assessment is met for any kind of drug.
Gene: Protein-coding gene on chromosome 17 (7,351,889 to 7,354,944, forward strand). Ensembl gene ENSG00000213859.
Subcellular location (Human Protein Atlas): Nucleoplasm
Gene Ontology:
Molecular function: identical protein binding
Biological process: positive regulation of neuron differentiation; protein homooligomerization; protein ubiquitination
Cellular component: cytoplasm
Genetic constraint (gnomAD): Loss-of-function variants: 8 observed, 11.54 expected, observed/expected ratio (o/e) 0.69, 90% interval 0.41 to 1.25. The upper end of that interval is the gene's LOEUF score, 1.25, which puts it in group 5 of 6, group 1 being the genes least tolerant of losing a copy. Missense variants: 307 observed, 328.93 expected, observed/expected ratio (o/e) 0.93, 90% interval 0.85 to 1.03. Synonymous variants: 133 observed, 145.51 expected, observed/expected ratio (o/e) 0.91, 90% interval 0.79 to 1.06.
Homologues: Orthologues: pig KCTD11 (93% identical), dog KCTD11 (92% identical), chimpanzee KCTD11 (85% identical), macaque KCTD11 (83% identical), rat Kctd11 (78% identical), mouse Kctd11 (77% identical), Drosophila melanogaster twz (23% identical), Caenorhabditis elegans F32B4.5 (15% identical). Paralogues in human: KCTD21 (41% identical), KCTD6 (28% identical), KCTD4 (25% identical), KCNRG (24% identical), KCTD7 (23% identical), KCTD19 (22% identical), KCTD1 (22% identical), KCTD15 (21% identical), KCTD8 (20% identical), KCTD12 (20% identical), KCTD18 (20% identical), KCTD16 (19% identical), and 1 more.
Diseases named in the same sentence as KCTD11 in open-access papers:
KCTD11 is named in the same sentence as 25 diseases in open-access papers, as found by Europe PMC text mining. Sharing a sentence is not in itself a finding about the gene and the disease. The quoted sentences say what the papers report.
medulloblastoma (5 papers, 2010 to 2024). A malignant, invasive embryonal neoplasm arising from the cerebellum. "Among the 25 human KCTD family members, several have been linked to human cancers, including KCTD8, KCTD12, TNFAIP1 and most notably KCTD11/Ren/KCASH1, a reported tumor suppressor in medulloblastoma, possibly by suppressing Hedgehog signaling." (PMID 30142151, 2018). "We have recently demonstrated that KCTD11 expression is frequently lost in human medulloblastoma (MB), in part by LOH and in part by uncharacterized epigenetic events." (PMID 20591193, 2010). "KCTD11 was reported to suppress the Hedgehog signaling pathway in medulloblastoma, and crosstalk between the Hedgehog and PI3K/AKT/mTORC1 pathways via Gli1 activation has been reported to occur in several types of cancer models including medulloblastoma, prostate cancer and breast cancer cell lines." (PMID 30142151, 2018). "Importantly, KCTD11 has been further characterized as a tumor suppressor gene mapping on human chromosome 17p13.2, whose expression is frequently lost in human medulloblastoma and in several other cancer types due to both LOH and epigenetic events." (PMID 25045667, 2014). "In addition, it has been demonstrated that KCTD11 acts as a negative regulator of the Hedgehog (Hh) signaling in human medulloblastoma." (PMID 25045667, 2014). "Importantly, the human orthologue of murine KCTD11 has been shown to be frequently lost in human medulloblastoma (MB)." (PMID 25045667, 2014). "Notably, KCTD11 downregulation is associated with Gli1 and Patch1 overexpression, demonstrating that KCTD11 tumor suppressor gene acts as an inhibitor of Hedgehog signaling not only in medulloblastoma but also in prostate cancer." (PMID 25045667, 2014). "KCTD11 (REN) is a tumor suppressor gene mapping on human chromosome 17p13.2, whose expression is frequently lost in human medulloblastoma and in several other cancer types." (PMID 25045667, 2014).
prostate adenocarcinoma (3 papers, 2014 to 2018). "KCTD11 also has been implicated as a tumor suppressor in several other cancers including prostate adenocarcinoma, and hepatocellular carcinoma, although its role in cancer remains to be confirmed." (PMID 30142151, 2018). "Though the tumor suppression role of KCTD11 has been described in human MB and prostate adenocarcinoma, intensive and systematic researches are still needed to illuminate the value of this molecule in study and treatment of tumors." (PMID 28465479, 2017). "Decreased expression of KCTD11 was found in some tumors such as human MB and prostate adenocarcinoma." (PMID 28465479, 2017). "Here, we demonstrated that KCTD11 LOH is a common genetic lesion also in human prostate adenocarcinoma." (PMID 25045667, 2014). "Here, we demonstrated that KCTD11 LOH is a common genetic lesion in human prostate adenocarcinoma." (PMID 25045667, 2014). "However, different from other tumors such as human MB and prostate adenocarcinoma, neither enhancing expression of p27Kip1 nor antagonizing Hedgehog signaling by regulating Gli1 has be found in HCC cells after KCTD11 overexpression (data not shown)." (PMID 28465479, 2017).
lung carcinoma (2 papers, 2021 to 2023). "The possibility of hypermethylation, mutation or enhanced metabolism of the KCTD11 gene in lung cancer cells requires further experimental research and verification." (PMID 34453479, 2021). "By co‐immunoprecipitation and immunofluorescence, we found that KCTD11 can bind to β‐catenin and co‐localize in lung cancer tissues and cells." (PMID 34453479, 2021). "KCTD11 is under‐expressed in lung cancer tissues and cells and was negatively correlated with the degree of differentiation, tumour‐node‐metastasis (TNM) stage and lymph node metastasis." (PMID 34453479, 2021). "The effect of KCTD11 on the biological behaviour of lung cancer cells was verified in vitro and in vivo." (PMID 34453479, 2021). "In vivo and in vitro experiments demonstrated that the overexpression of KCTD11 in lung cancer cell lines significantly inhibited the proliferation and migration of lung cancer cells, with the opposite results seen after knockdown." (PMID 34453479, 2021). "In this study, we first detected that the expression of KCTD11 in lung cancer specimens was decreased by immunohistochemical methods." (PMID 34453479, 2021). "Overall, the present study found that KCTD11 binds to β‐catenin and inhibits β‐catenin nuclear translocation which further inhibits the Hippo pathway, thus leading to decreased proliferation and metastasis of lung cancer cells." (PMID 34453479, 2021). "In this study, we first verified the level of KCTD11 expression in lung cancer tissues and cells." (PMID 34453479, 2021). "KCTD11 overexpression inhibited the proliferation and migration of lung cancer cells." (PMID 34453479, 2021). "Therefore, in order to study the molecular mechanism by which KCTD11 affects the malignant phenotype of lung cancer, we explored the effect of KCTD11 on the expression level of Hippo pathway and Wnt pathway‐related proteins." (PMID 34453479, 2021). "We also investigated the effects of KCTD11 on the proliferation and invasion of lung cancer cells." (PMID 34453479, 2021). "The Kaplan‐Meier database also showed that KCTD11‐positive patients survived significantly longer than KCTD11‐negative patients, suggesting that KCTD11 expression can be considered as a prognostic factor in lung cancer." (PMID 34453479, 2021). "Therefore, KCTD11 constitutes the link between the Wnt and Hippo pathways, and may be a potential target for lung cancer drug development." (PMID 34453479, 2021). "The tumor suppressor KCTD11 is down-regulated in NSCLC and KCTD11 overexpression inhibits lung cancer progression by binding to β-catenin to regulate the activity of the Wnt and Hippo pathways." (PMID 37537569, 2023). "However, the reason for low KCTD11 expression in non‐small cell lung cancer remains unclear." (PMID 34453479, 2021). "The results of this study indicate that the human potassium channel tetramer protein KCTD11 can bind to β‐catenin through its BTB domain in NSCLC cells, inhibit the Wnt pathway, increase Hippo pathway activity, and inhibit the proliferation and migration of lung cancer cells." (PMID 34453479, 2021). "However, the expression of KCTD11 in lung cancer and its possible biological effects have not been reported." (PMID 34453479, 2021). "However, the expression of KCTD11 and its role has not been reported in human non‐small cell lung cancer (NSCLC)." (PMID 34453479, 2021).
prostate carcinoma (2 papers, 2014 to 2018). A carcinoma that arises from epithelial cells of the prostate gland. "Here, we showed both LOH and decreased protein expression of the tumor suppressor gene KCTD11 in prostate cancer, which is associated with increased expression of Hh proteins." (PMID 25045667, 2014). "Taken together, these data suggest that KCTD11 can be considered a potential candidate to be used for diagnostic and therapeutic application in prostate cancer." (PMID 25045667, 2014). "In this work, we identified KCTD11 as a gene frequently lost in prostate cancer, showing both LOH and decreased protein expression." (PMID 25045667, 2014). "Our study demonstrates and supports that KCTD11, as well as negatively regulated downstream effectors belonging to Hh signaling, plays a role in prostate cancer pathogenesis." (PMID 25045667, 2014). "KCTD11 expression in prostate cancer cells was also quite low, and ectopic overexpression of KCTD11 determined growth arrest through cyclin-dependent kinase inhibitors upregulation and Hedgehog/Gli target genes' downregulation." (PMID 25045667, 2014). "Low levels of KCTD11 mRNA have been also observed in prostatic cancer cells, and ectopic overexpression of KCTD11 led to growth arrest." (PMID 25045667, 2014). "KCTD11 expression in prostatic cancer cells was also quite low, and ectopic overexpression of KCTD11 determined growth arrest through cyclin-dependent kinase inhibitors' upregulation and Hedgehog/Gli target genes' downregulation." (PMID 25045667, 2014). "Indeed, nuclear KCTD11 protein expression is strongly reduced in primary prostate cancer, and this event correlated with overexpression of proteins acting into the Hedgehog pathway." (PMID 25045667, 2014). "In addition, KCTD11 overexpressing prostate cancer cells displayed a reduction of cell proliferation-related genes, which are known direct targets of Hedgehog/Gli1, such as Cyclin D2 and IGF-2." (PMID 25045667, 2014). "Indeed, nuclear KCTD11 protein expression is strongly decreased in primary prostate cancer, and this event is correlated to overexpression of proteins acting into the Sonic Hedgehog pathway." (PMID 25045667, 2014).
acute lymphoblastic leukemia (1 paper, 2023). Leukemia with an acute onset, characterized by the presence of lymphoblasts in the bone marrow and the peripheral blood. "Thus, among all the KCTDs examined, only two pairs of them seem to be able to discriminate not only between the ALL subtype and the relative healthy counterpart, but also between the two types of acute lymphoblastic leukemia: KCTD12 and KCTD3 for B-ALL, and KCTD1 and KCTD11 for T-ALL." (PMID 37297863, 2023).
autism (1 paper, 2019). Persistent deficits in social interaction and communication and interaction as well as a markedly restricted repertoire of activity and interest as well as repetitive patterns of behavior. "Varying levels of evidence support their roles in neurocognitive disorders (KCTD3), neurodevelopmental disease (KCTD7), bipolar disorder (KCTD12), autism and schizophrenia (KCTD13), movement disorders (KCTD17), cancer (KCTD11), and obesity (KCTD15)." (PMID 31197948, 2019).
blastoma (1 paper, 2016). A malignant neoplasm composed of undifferentiated cells. "Kctd11 functional knock-down was shown to impair Hedgehog antagonism resulting in sustained proliferation of granule progenitor cells, a mechanism responsible for medullo-blastoma development." (PMID 27121005, 2016).
colon cancer (1 paper, 2010). "To evaluate whether methylation might regulate KCTD11 transcription, we investigated the effects of demethylation on KCTD11 expression, in two human colon cancer cell lines, HCT15 and HCT116." (PMID 20591193, 2010).
leukemia (1 paper, 2023). A malignant (clonal) hematologic disorder, involving hematopoietic stem cells and characterized by the presence of primitive or atypical myeloid or lymphoid cells in the bone marrow and the blood. "KCTD11 cannot significantly discriminate either between leukemia types or individual leukemia from healthy controls." (PMID 37297863, 2023). "On the other hand, the transcriptomic analysis of T-ALL patients highlighted KCTD1, KCTD9, KCTD11, and KCTD15 to be upregulated in pediatric leukemia patients." (PMID 37297863, 2023).
liver cancer (1 paper, 2017). An epithelial or non-epithelial malignant neoplasm that arises from the liver. "We further compared the protein expression of KCTD11 in an immortalized normal liver cell line (QSG-7701) and four liver cancer cell lines (HepG2, Huh7, HCCLM3, SK-Hep-1) by western bolt." (PMID 28465479, 2017).
pancreatic cancer (1 paper, 2021). "Among them, the mRNA levels of ADM, C4orf3, ERO1L, FUT11, BNIP3L, NDRG1, KCTD11, SLC2A1, and P4HA1 were increased in pancreatic cancer tissues compared to adjacent pancreatic tissues from TCGA and GTEx database." (PMID 34221996, 2021).
tumor (13 papers, 2010 to 2024). "Mutations within the components of the HH pathway, for example, membrane receptor proteins PTCH1 and SMO, non-membrane receptor proteins, such as SUFU and REN (KCTD11), disrupt the feedback loop causing activation of HH pathway and tumor progression." (PMID 33637972, 2021). "In further studies, we directly knocked out the BTB domain and found that KCTD11 cannot bind to β‐catenin, thus losing its role as a tumour suppressor." (PMID 34453479, 2021). "The expression of KCTD11 was negatively correlated with the degree of tumour differentiation, high TNM stage and lymph node metastasis in patients with NSCLC." (PMID 34453479, 2021). "Western blot analysis and dual‐luciferase assay confirmed that the BTB domain is a KCTD11 functional region, which affects the role of KCTD11 in tumour suppression." (PMID 34453479, 2021). "In summary, KCTD11 suppressed cell migration and invasion in vitro and inhibits tumor metastasis in vivo, by repressing MMPs and EMT." (PMID 28465479, 2017). "We found KCTD11 inhibiting cell proliferation in vitro and tumor growth in vivo, by activating p21 and repressing cycle related proteins." (PMID 28465479, 2017). "KCTD11 overexpression in HCCLM3 resulted in reduction of tumor volume and weight, and repressing Ki67." (PMID 28465479, 2017). "Overall, these results suggest that KCTD11 works as a tumor suppressor and owns prognostic and therapeutic potentials in HCC." (PMID 28465479, 2017). "With the results of assays in vitro and vivo, we demonstrate the tumor suppressing ability of KCTD11 in HCC." (PMID 28465479, 2017). "KCTD11 inhibits cell proliferation in vitro and tumor growth in vivo by activating p21 and repressing cycle related proteins." (PMID 28465479, 2017). "We found the tumor suppression function of KCTD11 was at least partly through activating Hippo pathway in HCC." (PMID 28465479, 2017). "So, we ascribe at least partly of the tumor suppression function of KCTD11 to enhanced Hippo pathway." (PMID 28465479, 2017). "Using a panel of human 177 tumor samples and their normal matching samples representing 18 different types of cancer, we show here that the down-regulation of KCTD11 protein level is a specific and a diffusely common event in tumorigenesis." (PMID 20591193, 2010). "KCTD11 has been reported to be a potential tumour suppressor in several tumour types." (PMID 34453479, 2021). "KCTD11 is a negative regulator of hedgehog pathway signalling and therefore its loss, identified using WGM, may increase signalling and imply this tumour would be sensitive to pathway inhibitors." (PMID 32392735, 2020). "KCTD11 knock-down in Huh7 increased tumor volume and weight, and promoted Ki67 expression." (PMID 28465479, 2017). "In summary, we identify KCTD11 as a tumor suppressor in HCC." (PMID 28465479, 2017). "In this study, the down-regulation of KCTD11 in HCC tissues and cell lines suggests KCTD11 could be a tumor suppress gene and may possess important function in normal liver cells." (PMID 28465479, 2017). "The protein levels of KCTD11 was also found lower in tumor tissues than peritumoral tissues." (PMID 28465479, 2017). "The tumor suppression function of KCTD11 is at least partly in a way of activating Hippo pathway." (PMID 28465479, 2017). "Our findings identify KCTD11 as a widely down-regulated gene in human cancers, and provide a basis to understand how its expression might be deregulated in tumor cells." (PMID 20591193, 2010). "The aberrantly expression of KCTD11 suggested that KCTD11 may be a tumor suppress gene in HCC." (PMID 28465479, 2017).